RAC3 (Rac family small GTPase 3)
Diseases named in the same sentence as RAC3 in open-access papers (continued):
Sharing a sentence is not in itself a finding about the gene and the disease.
cancer (continued). "Activated Rac3 has been linked to deregulated p21-activated kinase (Pak) and c-Jun N-terminal kinase (JNK) activities in human cancer cells." (PMID 18826651, 2008). "The discovery that RAC3 may function as an oncogene highlights its influence on cancer development, suggesting that it could be a key player in the intricate dance of oncogenesis." (PMID 39351351, 2024). "This may also be an isoform dependent effect because cancer cells express Rac1 and Rac3, while hematopoietic cells express Rac2." (PMID 37397366, 2023). "RAC3 was also embroiled in cancer cell proliferation and aggressiveness." (PMID 35125116, 2022). "Interestingly, Ehop-016, a Rac1 and Rac3 inhibitor, significantly reduced Ser2P and Ser5P levels in both cancer cell lines, although it also slightly reduced Ser7P in HeLa cells." (PMID 32143485, 2020). "Our findings demonstrated that RAC3 overexpression as the unique introduced genetic modification in non tumoral cells, induced a cell transformation toward a phenotype that suggests the presence of cancer stem cells." (PMID 29464039, 2018). "In view of these results, we wanted to know if RAC3 could have a role inducing or maintaining some phenotypic properties of cancer stem cells that are shared with mesenchymal cells." (PMID 29464039, 2018). "Although the mechanism by which RAC3 is overexpressed, as a conserved signal in such amount of tumors remains unclear, it is possible to speculate this is a cancer stem cell condition, then heritable to the heterogeneous tumoral progeny." (PMID 29464039, 2018). "In addition to the well-studied Rac1, we also report the importance of Rac2 and Rac3 in the regulation of cancer stemloids." (PMID 28160553, 2017). "Mutations in the Rac3 gene have been identified from a range of cancers, including melanoma, stomach and prostate, but none has yet been studied functionally." (PMID 27104658, 2016). "However, most of literature addressing the role of Rac in cancer progression concern Rac1, with little mention of Rac3." (PMID 24684802, 2014). "Moreover, we tested the effect of Rac3 depletion on capillary-like structure formation (VM) by cancer cells plated on Matrigel rich in growth factors." (PMID 23388133, 2013). "However, most of the literature addressing the role of Rac in cancer aggressivity concerns Rac1, and studies on the role of Rac3 in cancer progression are far less abundant." (PMID 23388133, 2013). "This indicates that Rac3 is involved in the cancer cells’ aggressiveness." (PMID 23388133, 2013). "However, RAC3 has important but not fully understood biological functions in cancer." (PMID 35847878, 2022). "However, when the ABC transporters were blocked, although the total stain retention was increased, the amount of unstained cells was significantly inhibited in shRAC3 cells respect to control, demonstrating a decrease of cancer stem cell population in cells having low expression levels of RAC3." (PMID 29464039, 2018). "Although the requirement of RAC3 expression for normal stem cells has been demonstrated, the consequences of overexpression over them, remains as an intriguing question to be investigated in order to improve the strategies for anti-cancer treatments and also that involving stem cell therapies." (PMID 29464039, 2018). "Therefore, integrating all our previous and present results it is not surprising a probably association of RAC3 overexpression with a cancer stem cells." (PMID 29464039, 2018). "Rac2-KO and Rac3-KO mice showed slightly increased survival in a CML and ALL background, respectively, suggesting a possible oncogenic role for these genes; further experimentation will be required to determine the functional significance of these cancer-associated mutations." (PMID 27104658, 2016). "However, the role of Rac3 in cancer aggressiveness is less well understood." (PMID 23388133, 2013).
cancer (continued). "Moreover, the possible interrelations between the different Rho and Rac proteins led us to examine the effects of Rac3 inhibition on activation of other Rho proteins that could potentially influence the aggressiveness cancer cells." (PMID 23388133, 2013). "When hypomethylated, RAC3 can promote cell proliferation and invasion by increasing FASN expression in EC, potentially serving as a link between these two cancer types." (PMID 40564925, 2025). "Of these, ALDOB, WNT11, MSLN, RAC3, and IL1RN have known roles in CRC, FBLX16 has known roles in other cancers, and SLC38A11 and WBSCR27 are relatively uncharacterized." (PMID 38680862, 2024). "The analysis of heatmaps revealed that PDGFRA and PTPRR demonstrated high SNV across various cancers, whereas PTPRR and RAC3 exhibited elevated CNV in the majority of cancer types." (PMID 38714855, 2024). "SETD8 serves as an unfavorable indicator of prognosis for ES patients, as it stimulates the growth of cancer cells and curbs both apoptosis and ferroptosis through the YBX1/RAC3 pathway." (PMID 38987564, 2024). "Survival analysis of Overall Survival (P=0.003) and Cancer Specific Survival (P<0.001) from GSE13507, as well as Cancer Specific Survival (P<0.001) provided by GSE32849 validated the poor outcome of patients with high RAC3 expression." (PMID 35847878, 2022). "Rac family of small GTPase 3 (RAC3), also called ras-related C3 botulinum toxin substrate 3, is a member of the Rho GTPases family, including RAC1, RAC2, and RAC3, which plays a critical role in cancer progression." (PMID 33062641, 2020). "Our results demonstrate that although RAC3 overexpression could be a signal strong enough to induce cancer stem cells, the inflammatory microenvironment may be playing a key role contributing to the migratory and invasive phenotype required for metastasis and cancer persistence." (PMID 30585274, 2018). "The decrease in IL-10 secretion induced by anti-Rac3 siRNA can also be explained by the action of Rac3 on ERK-2/NF-κB signaling, but its role in cancer aggressivity has been reported to be due mainly to an immunosuppression and also to its angiogenic activity." (PMID 23388133, 2013). "As the vasculogenic mimicry process is a marker of cancer cell aggressiveness, and as it has been shown to depend on MMP-9 secretion, the effect of Rac3 depletion on vasculogenic mimicry was also tested." (PMID 23388133, 2013). "RAC2 also showed upregulation of proliferative pathways, including signalling by NTRK2/TRKB, characterised by overexpression of the PIK3CA gene, and signalling by ERBB2 in cancer, as reflected by elevated serum concentrations of SHC1, ERBB4, EGFR and ERBB2, compared with RAC3." (PMID 39401856, 2024). "Unlike RAS proteins, which are frequently mutated in cancer (around 30%), RAC proteins (RAC1, RAC2 or RAC3) themselves are generally not found to be mutated in cancers at such a high frequency." (PMID 31027363, 2019). "In contrast, in MCF-7, Rac3 does not increase cancer aggressivity despite the fact that Rac3 activates ERK in these cells." (PMID 23388133, 2013). "The decrease in MMP-9 secretion following treatment with siRNA anti-Rac3 can also be involved in its inhibitory effect on VM in MDA-MB-231 cells, as it was described that both MMP-2 and MMP-9 play an important role in VM in cancers." (PMID 23388133, 2013). "The effect of Rac3 in cancer cells was also compared with its effect on the non-tumorigenic mammary epithelial cells MCF-10A." (PMID 23388133, 2013).
tumor (41 papers, 2011 to 2025). "Rac3 is highly expressed in the brain and has been implicated in neuronal development and tumor progression." (PMID 38884093, 2024). "Cheng and his colleagues found that elevated RAC3 expression is associated with adverse clinical outcomes and an increased tumor immune response." (PMID 38217031, 2024). "Subsequently, RAC3 was associated with poor prognosis in EC via its immunosuppressive phenotype and the regulation of tumour cell viability." (PMID 37386813, 2023). "In the GSE32894 dataset, we found that expression of Rac3 was significantly associated with the tumor grade (p = 6.626e − 06) and stage (p = 0.004)." (PMID 34257551, 2021). "Cox multivariate analyses showed that Rac3 was independently associated with OS (HR: 1.019, 95% CI = 1.007–1.031, p = 0.002), and other factors affecting OS were age and tumor stage." (PMID 34257551, 2021). "In the 'Lee Bladder' dataset, we also found that the expression of Rac3 was significantly associated with the tumor grade (p = 0.031)." (PMID 34257551, 2021). "Rac3 expression was significantly associated with the tumor grade (p = 0.03), as its expression increased with the grade." (PMID 34257551, 2021). "RAC3 overexpression usually accompanies tumor development which involves several mutations and chromosome aberrations." (PMID 30585274, 2018). "Our research highlights the significant association of RAC3 with key biological processes, including the promotion of cell proliferation, migration, invasion, and somatic growth, as well as its influence on the tumor microenvironment (TME) and immune response." (PMID 39351351, 2024). "Importantly, the high percentage of tumour‐cell staining and the AUC values close to 1 supported RAC3 as a good diagnostic marker in EC." (PMID 37386813, 2023). "In this paper, we revealed that RAC3 was predominantly expressed in EC and significantly correlated with the progression of EC via inducing immunosuppression and regulating tumour cell viability, providing a novel diagnostic biomarker and a promising strategy for sensitizing chemotherapy to EC." (PMID 37386813, 2023). "The mRNA level of RAC3 had good diagnostic accuracy, with an AUC of ROC reached 0.944 (95% CI = 0.910-0.978), which could better discriminate tumor and non-tumor samples." (PMID 35847878, 2022). "High expression of RAC3 is associated with advanced tumor characteristics and poor prognosis." (PMID 35847878, 2022). "Therefore, in this context, the induction of malignant or premalignant lesions from cells acquiring this RAC3 overexpression and possible additional mutations or epygenomic rearrangements sounds as a possible source for tumor initiating cells." (PMID 29464039, 2018). "Additional functions related to tumor progression and metastasis development, such as metalloproteinases expression, cell migration and epithelial-mesenchymal transition have also been described and attributed to the RAC3 splicing variant Delta 4-SRC3." (PMID 29464039, 2018). "Taken together, all these results demonstrate that RAC3 is an inhibitor of senescence whose downregulation in aged individuals could be probably a tumor suppressor mechanism, avoiding the clonal expansion of risky old cells having damaged DNA." (PMID 26469953, 2015). "Cox univariate analyses showed that Rac3 expression was associated with poor prognosis (hazard ratio [HR]: 1.280, 95% confidence interval [CI] = 1.091–1.502, p = 0.002), and other clinical variables associated with poor survival included age, tumor stage and N stage." (PMID 34257551, 2021). "Immunohistochemistry analysis corroborated that high expression of Ki‐67 was detected in RAC3 overexpression tumor tissues, while the opposite effect was observed in the RAC3 knockdown group." (PMID 40123831, 2025).
tumor (continued). "We then constructed a tumor metastasis model that MHCC97H or HCCLM3 stably expressing firefly luciferase with RAC3 stable overexpression or silencing was injected via the tail vein into NCG (NOD/ShiLtJGpt‐Prkdcem26Cd52Il2rgem26Cd22/Gpt) mice." (PMID 40123831, 2025). "Correlation analysis between RAC3 protein expression and clinicopathological parameters indicated significant links between high RAC3 expression and tumors larger than 3 cm (p = 0.049), tumor recurrence (p = 0.034), and OS (p = 0.001)." (PMID 40123831, 2025). "To further validate the relationship between RAC3 and gemcitabine sensitivity, we collected tumor tissue paraffin specimens from 20 patients with NMIBC who received intravesical gemcitabine instillation postoperatively." (PMID 38570787, 2024). "It was also shown that RAC3 promotes tumor cell resistance to chemotherapeutic drugs by inhibiting apoptosis and autophagy." (PMID 37728806, 2024). "Our findings indicate a significant increase in RAC3 gene expression within the tumor tissues compared with the surrounding normal tissue samples." (PMID 39351351, 2024). "Studies have demonstrated that RAC3 enhances tumor cell proliferation, migration, and invasion by activating the JAK/STAT signaling pathway." (PMID 38714855, 2024). "Since the survival and differential expression analysis results showed that both FASN and RAC3 were highly expressed in tumor tissues, the next step was carried out." (PMID 39659999, 2024). "We further explored the impact of RAC3 knockdown on tumor growth in vivo using a subcutaneous xenograft model in nude mice." (PMID 39659999, 2024). "Cells expressing shRAC3-2 and non-targeting control shCtrl were injected, and the results demonstrated significant inhibition of tumor growth upon RAC3 knockdown." (PMID 39659999, 2024). "Overall, RAC3 was significantly correlated with the progression of EC by inducing immunosuppression and regulating tumour cell viability." (PMID 37386813, 2023). "According to apoptosis‐related GSEA analysis, RAC3 also modulated the apoptosis process of EC tumour cells." (PMID 37386813, 2023). "The results showed that RAC3‐positive cells were mainly enriched in tumour epithelial regions than in stromal regions." (PMID 37386813, 2023). "Among the 33 tumour subtypes archived in TCGA cohorts, 15 kinds had statistically significant RAC3 expression differences between tumour and normal tissues, including EC." (PMID 37386813, 2023). "Based on TCGA, single‐cell RNA‐Seq, CCLE and clinical specimens, we revealed that the RAC3 was specifically distributed in EC tumour cells compared to normal tissues and functioned as an independent diagnostic marker with a high area under curve (AUC) score." (PMID 37386813, 2023). "The results indicated that RAC3 was highly expressed in tumour tissues but had limited expression in normal tissues." (PMID 37386813, 2023). "RAC3 was an understudied paralog of the canonical RAC1 GTPase and was implicated in tumor cell proliferation and invasion." (PMID 36936912, 2023). "Immunohistochemistry assay showed that CAFs increased the expression of METTL3 and RAC3 in tumor tissues." (PMID 37056933, 2023). "In our study, RAC3 was significantly upregulated in tumor samples and exhibited widespread CNV alterations." (PMID 36936912, 2023). "AP2S1, P3H4 (SC65), SPAG4, PLA2G2F, PTPN6, RAC3, and ETV7 were identified as candidate tumor-associated antigens." (PMID 35814377, 2022). "Another marker identified by our protocol, RAC3, is involved in neuronal development and in tumor progression, by modulating the organization of the cytoskeleton, cell migration, cell proliferation, and reactive oxygen species production." (PMID 35806060, 2022). "AP2S1, P3H4, and RAC3 were identified as candidate tumor-specific antigens, and patients with the BCS2 and BCS1A subtypes were identified as candidate populations for mRNA vaccines." (PMID 35814377, 2022).
tumor (continued). "Based on the in vitro results, the in vivo proliferation suppressive effect of RAC3 depletion was determined in a xenograft tumor model by subcutaneous injection of 5637-shNC/shRAC3 cells." (PMID 35847878, 2022). "Autophagy is a tumor-suppressive mechanism that maintains genomic integrity and suppresses tumorigenesis, as occurs with RAC3 knockdown cells." (PMID 35847878, 2022). "Compared with non-tumor samples, RAC3 was highly expressed in BCa and negatively correlated with prognosis." (PMID 35847878, 2022). "By regulating this signaling network, Rac3 participates in balancing adhesion with the proteolytic activity at invadopodia to optimize tumor cell invasion." (PMID 31514269, 2019). "Silencing of Rac3 also inhibits proliferation and the formation of colonies by A549 lung cancer cells in vitro and induces a strong increase in tumor cell apoptosis." (PMID 31514269, 2019). "On the other hand, the implication of the closely related Rac3 GTPase in tumor progression is becoming evident by the experimental evidence that has been accumulating over the past years." (PMID 31514269, 2019). "Increasing evidence over the past few years indicates that Rac3 plays an important role in neuronal development and in tumor progression, with specificities that distinguish the functions of Rac3 from the established functions of Rac1 in these processes." (PMID 31514269, 2019). "Five aberrantly methylated genes (epidermal growth factor, EGF; carbohydrate sulfotransferase 10, CHST10; ependymin related 1, EPDR1; bone marrow stromal antigen 2, BST2; and Rac family small GTPase 3, RAC3) were further verified in CRC tumor tissues." (PMID 30360391, 2018). "Most of the studies that allowed to define RAC3 as an oncogene were performed in models where it is naturally overexpressed, such as tumoral cell lines, tumors and transgenic or knockout mice where expression is equally affected in all the tissues." (PMID 29464039, 2018). "RAC3 is an oncogene having nuclear and cytoplasmic functions usually overexpressed in several tumor types, but having very low or undetectable expression levels in normal mature differentiated cells." (PMID 29464039, 2018). "The inhibition of Rac3 expression in MDA-MB-231 cells blocked the VM; this provides yet another argument for thinking that Rac3 plays a role in tumour aggressiveness, even in cells where the small GTPase RhoA is overexpressed and spontaneously activated." (PMID 23388133, 2013). "Rac3 GTPase has clearly been shown to be involved in adhesion of tumor and normal cells of neural origin." (PMID 21776386, 2011). "In the current study, we set out to determine the individual roles of Rac1, Rac3, and RhoG in tumor cell diapedesis." (PMID 21776386, 2011). "Moreover, our HCC tissue microarray analysis consistently demonstrated that RAC3 was up‐regulated in HCC and associated with the tumor size, tumor recurrence, and survival." (PMID 40123831, 2025). "In contrast, RAC3 levels were significantly reduced in tumor tissues of KICH, KIRC, KIRP, and THCA." (PMID 40123831, 2025). "Several studies have demonstrated that RAC3 facilitates malignant tumor behaviors." (PMID 40123831, 2025). "RAC3 overexpression markedly escalated the tumor mass by day 21 post‐inoculation." (PMID 40123831, 2025). "Taken together, these findings imply that RAC3 may serve as a tumor promoter, driving hepatocarcinogenesis and the malignancy of HCC by activating the cAMP/MAPK/Rap1 signaling pathway through NNMT." (PMID 40123831, 2025). "IHC staining was used to validate the expression of RAC3 in BCa tumor tissue." (PMID 38570787, 2024). "RAC3 is a tumor-promoting factor that can promote the proliferation, migration, and invasion of BLCA, and may be related to the activation of the PYCR1/JAK/STAT signaling pathway." (PMID 39659999, 2024). "In general, RAC3 exhibits high expression levels in most tumours of epithelial origin." (PMID 37386813, 2023).